IL6 (interleukin 6)
Diseases named in the same sentence as IL6 in open-access papers (continued):
Sharing a sentence is not in itself a finding about the gene and the disease.
ovarian carcinoma (continued). "Therefore, the higher IL6 serum levels may also explained the association of pro-inflammatory mediator in the development of advanced ovarian epithelial cancer." (PMID 37792745, 2023). "In 2005, for the first time, we reported that, in a population of advanced ovarian cancer assessed at diagnosis prior to any antineoplastic treatment, the severity of cancer-related anemia was associated with a status of chronic inflammation characterized by high levels of IL-6, CRP, and fibrinogen." (PMID 33550983, 2021). "Moreover, hepatic IL-6 induces the synthesis of hepcidin, ultimately causing functional iron deficiency, chronic inflammation-associated anemia, and thrombopoietin, which induces thrombocytosis, as specifically demonstrated in ovarian cancer." (PMID 33550983, 2021). "Similarly, evidences demonstrate that overexpression of HOTAIR could cause platinum resistance of ovarian cancer by inducing NF-κB and downstream target gene, interleukin-6 (IL-6)." (PMID 32245498, 2020). "Notably, ovarian cancer-associated fibroblast-derived IL-6 contributed to its up-regulation." (PMID 31212816, 2019). "Thus, there may be a complex reciprocal regulation between AR signaling and IL-6/IL-8 during the carcinogenesis of ovarian cancer and further study is necessary to elucidate the underlying mechanisms." (PMID 27741511, 2017). "Treatment of EOC cells with the anti-IL6 antibody (Ab) siltuximab has been shown to reduce constitutive cyto/chemokine production and inhibit IL6 signaling, tumor growth, the tumor-associated macrophage infiltrate, and angiogenesis in IL6–producing intraperitoneal ovarian cancer xenografts." (PMID 23889749, 2013). "For in vivo studies, ID8-F3 murine ovarian cancer cells expressing mouse IL6/1 (mIL6/1) were administered intraperitoneally (I.P.)as a cell-based therapy to C57BL/6 female mice bearing established ID8-F3 luciferase tumors." (PMID 42146708, 2026). "Through the IL‐6/STAT3/HIF‐1α feedback loop, IL‐6 aggravates cisplatin resistance in ovarian cancer cells." (PMID 40968783, 2026). "Among the cytokines most highly regulated by the ET-1/ETAR-activated GSDME/ZEB1 signaling network, we noted interleukin (IL)-6, a gatekeeper of cancer cell/TME communication implicated in ovarian cancer growth, metastasis and immune evasion." (PMID 41545335, 2026). "TA-MSCs from tumors like osteosarcoma, breast cancer, ameloblastoma, gastric cancer, glioma, and ovarian carcinoma, promote tumor cell stemness by releasing factors such as IL-6, IL-15, R-spondin, exosomal miR-1587, BMP, and LIF." (PMID 40676710, 2025). "MiR-217 inhibits M2-like macrophage polarization in ovarian cancer by directly targeting and suppressing the secretion of IL-6, a key cytokine involved in promoting this immunosuppressive macrophage phenotype." (PMID 40330466, 2025). "In ovarian cancer tissues and cell lines, miR-217 is downregulated, which leads to increased IL-6 secretion and the activation of the JAK2/STAT3 signaling pathway, driving M2-like macrophage polarization." (PMID 40330466, 2025). "Ovarian cancer cells can secrete IL-6, and serum and ascites IL-6 levels are significantly elevated in ovarian cancer patients." (PMID 40661780, 2025). "In conclusion, IL6 plays a pivotal role in shaping the inflammatory microenvironment of ovarian cancer, influencing both tumor biology and clinical outcomes." (PMID 40427188, 2025). "Third, the omenta from patients with endometriosis and benign cyst produced lower levels of VEGF-A and IL-6 compared to ovarian cancer." (PMID 40076450, 2025). "IL6 is a crucial mediator of the inflammatory response within the ovarian cancer tumor microenvironment (OC-TME)." (PMID 40427188, 2025). "Overexpression ABCB1, FGF2, CXCR4, and IL6 portends aggressive ovarian cancer behaviors and poor prognoses." (PMID 40507922, 2025).
ovarian carcinoma (continued). "Research findings show that compared with the healthy control group, the levels of C-reactive protein (CRP) and interleukin-6 (IL-6) in patients with ovarian cancer are elevated." (PMID 40661780, 2025). "In contrast, among ovarian carcinoma cases, ascitic ROS levels showed a significant positive correlation with IL-6 concentrations." (PMID 40723209, 2025). "In ovarian cancer, M1 TAMs predominate and are stimulated by IL-6 to release hepcidin, a hormone that regulates iron homeostasis by restricting iron availability, which worsens anemia." (PMID 40330466, 2025). "Previous studies have shown that adipocyte-derived IL-6 activates hypoxia-inducible factor 1-alpha (HIF1α) in ovarian cancer, leading to increased tumor cell glycolysis." (PMID 40616161, 2025). "Machine learning and Artificial intelligence impact on Interleukin 6 for early, precise, and personalized Ovarian Cancer management." (PMID 40427188, 2025). "Cytokines such as tumor necrosis factor alpha (TNF-α) and interleukin-6 (IL-6) have been reported in subjects with many severe diseases, such as cervical carcinoma and ovarian cancer." (PMID 40136934, 2025). "The immune system, which can act against tumors, often supports tumor development in the ovarian cancer microenvironment through immunoevasion, which is influenced by cytokines such as IL-6, IL-10, and TGF-β." (PMID 40362280, 2025). "The microenvironment of ovarian cancer tumors is rich in IL-6, IL-10, and CSF-1, which promotes M2 polarization and the accumulation of M2 macrophages." (PMID 39981173, 2025). "Among these, only tocilizumab has shown concrete evidence of improving outcomes in ovarian cancer and acute myeloid leukaemia by targeting the IL-6 pathway." (PMID 39858048, 2025). "Below, we highlight the current conventional therapies, targeted treatments, and immunotherapies for ovarian cancer (OC), as well as the effect of adding IL6 blockade, each of which plays a crucial role in optimizing patient outcomes." (PMID 40427188, 2025). "In the context of advanced ovarian cancer, IL-6 is heavily involved in the tumor microenvironment, where it contributes to cancer-related anemia (CRA)." (PMID 40330466, 2025). "The microbiota–inflammation axis can be used as a biomarker for the early diagnosis of ovarian cancer (such as the LPS/IL-6 ratio in vaginal fluid) and as a new therapeutic target." (PMID 40732683, 2025). "IL6 serves as a valuable biomarker for diagnosing, predicting, and prognosticating ovarian cancer (OC), offering key insights into tumor behavior, treatment response, and patient survival." (PMID 40427188, 2025). "According to a recent study, patients with recurrent ovarian cancer exhibit increased levels of interleukin-6 and TNF-α in serum compared with levels in patients with NR ovarian cancer." (PMID 39135097, 2024). "Specifically, chronic stress elevates stress hormone levels, stimulates relative receptors, and subsequently decreases HDC expression, promoting ovarian cancer progression via the IL-6/STAT3/S100A9 pathway." (PMID 39720595, 2024). "This suggests that ovarian cancer has a direct effect on the kidney’s function, as the tumor led to increase in expression levels of IL-1β, TNFα, IL6, and GDF-15." (PMID 39394174, 2024). "Mesenteric fat secretes adipokines and cytokines such as leptin, adiponectin, TNF-α, and IL-6, creating a pro-inflammatory environment that drives ovarian cancer cell proliferation and migration." (PMID 39285292, 2024). "Studies suggest endometriosis as a contributing factor in ovarian cancer, with cytokines IL-2, IL-5, IL-6, IL-8, and IL-10 detected in serum, intra-cystic fluid, and peritoneal fluid in endometriomas and ovarian cancer patient samples." (PMID 39596309, 2024). "Several downstream mechanisms including PYK2, Ras/MEK/ERK, PI3K/Akt, and JAK/STAT3 signaling play a role in IL-6-mediated chemoresistance in ovarian cancers." (PMID 38932405, 2024).
ovarian carcinoma (continued). "Although the ability of (-)-loliolide to inhibit IL-6 activity and its potential as an anticancer agent for ovarian cancer is promising, further research is necessary to elucidate the mechanisms underlying its anticancer effects." (PMID 38998933, 2024). "For example, it upregulates CXCL8 and IL6 in ovarian cancer patients and CXCL10 expression in lung cancer cells." (PMID 39759512, 2024). "Among the isolates, compounds 1–3 were previously undescribed, and six of the isolates exhibited IL-6 inhibitory activity and antitumor potential in human ovarian cancer cell lines." (PMID 38998933, 2024). "Further studies demonstrated that IL-6 levels were significantly higher in ascitic fluid than in the serum of ovarian cancer patients, and the IL-6 levels correlated with higher ascites volume, tumor burden, and worse overall survival." (PMID 38689325, 2024). "Jagged2-expressing ovarian cancer cells interact with mesothelial cells and acquire a growth advantage in the tumor microenvironment by stimulating and releasing of IL-6 from omental mesothelial cells." (PMID 38575576, 2024). "There is also data suggesting that IL-6 is involved in chemoresistance in ovarian cancer, with higher levels of IL-6 seen after treatment with platinum chemotherapy in in vitro and murine models." (PMID 38689325, 2024). "IL-8 has the capacity to enhance the expression of EpCAM in ovarian cancer cells, while conversely, IL-6 exerts an inhibitory effect on this specific phenomenon." (PMID 38187284, 2024). "IL-6, IL-10, TNF-α, IFN-γ, TNF-α have been substantiated as directly linked to poor outcomes in epithelial ovarian cancer (EOC) patients." (PMID 38279997, 2024). "As in ovarian cancer, there are theoretical benefits to combining anti-IL-6 therapy with chemotherapy for GC-PC." (PMID 38689325, 2024). "Overall, these results indicated that HDC downregulation induced by stress hormones promoted the proliferation, migration, and invasion of ovarian cancer cells through activation of the IL-6/STAT3/S100A9 signaling pathway." (PMID 39720595, 2024). "Ovarian cancer has pre-clinical data suggesting that IL-6 promotes the survival of tumor cells and strengthens their resistance to chemotherapy through JAK/STAT signaling." (PMID 39125732, 2024). "Related studies on ovarian cancer also show that IL-6 mediates tumor cell proliferation and invasion." (PMID 38509620, 2024). "The experimental results suggest that prostaglandin E2 (PGE2) and IL-6 increased in cervical and ovarian cancer cell lines treated with carboplatin or cisplatin." (PMID 38787372, 2024). "For example, it has been observed to enhance IL-6 expression in ovarian cancer, consequently up-regulating PD-L1 expression in neutrophils, thereby accelerating tumor immune escape." (PMID 39049088, 2024). "Chronic stress leads to the downregulation of HDC expression, thereby facilitating the progression of ovarian cancer through the IL-6/STAT3/S100A9 pathway." (PMID 39720595, 2024). "A role for adipocyte-secreted interleukin-6 (IL-6) and interleukin-8 (IL-8) in the migration and invasion of ovarian cancer cells to omental tissue has been established in vitro." (PMID 39285292, 2024). "Specifically, lncRNA HOXA transcript at the distal tip (Hottip) in ovarian cancer cells has been shown to enhance the transcription and secretion of interleukin-6 (IL-6) by binding to c-jun." (PMID 39061147, 2024). "Treating ovarian cancer cell lines with an antisense IL-6 oligodeoxynucleotide resulted in decreased IL-6 production as well as an approximately 80% inhibition in cellular proliferation." (PMID 38689325, 2024). "Interleukin (IL)-6 is a major immunoregulatory cytokine present in the ovarian cancer microenvironment." (PMID 38998933, 2024).
ovarian carcinoma (continued). "The conditioned medium (CM) from visceral ASCs stimulates increased migration of ovarian cancer cells by activating JAK2-STAT3 through the secretion of IL-6 in a paracrine signaling pathway, in contrast to the results observed with CM from subcutaneous ASCs." (PMID 38540217, 2024). "A cytokine of particular interest in the gut microbiome is interleukin-6 (IL-6), found to be elevated in the ovarian cancer microenvironment." (PMID 38541242, 2024). "Very recently, we have shown that RV hampers glucose uptake and glycolysis while restoring autophagy in ovarian cancer cells exposed to IL-6." (PMID 38891879, 2024). "In the same study, an IL-6 neutralizing antibody enhanced the cytotoxicity effect of paclitaxel in mice, which further supports the need to target platelets in ovarian cancer to improve patients’ prognosis." (PMID 39518024, 2024). "Non-chemokine agents, such as HGF, stimulate the migration of ovarian cancer cells, while IL-6 supports this process in pancreatic cancer cells." (PMID 39595551, 2024). "BIRC3, a E3 ubiquitin-protein ligase that regulates NFkB activation and anti-apoptotic caspase regulation can be induced by IL-6 treatment in ovarian cancer cells." (PMID 39131380, 2024). "IL6 plays a pivotal role in ovarian cancer (OC) cells and promotes cancer progression by affecting mitochondrial dynamics." (PMID 39766086, 2024). "Studies show that IL6 treatment increases metastasis in ovarian cancer cell lines (SKOV3 and PA1) by activating Drp1, a key mitochondrial fission regulator." (PMID 39766086, 2024). "In this study, we identified IL-6-targeting and -inhibitory compounds using isolates from P. attenuatum and evaluated their antitumor activity, particularly in ovarian cancer." (PMID 38998933, 2024). "Further research is necessary to fully understand IL-6’s complex interactions with ovarian cancer and to explore its potential in developing new treatment strategies." (PMID 39061859, 2024). "Translational research and clinical trials of IL-6 pathway inhibition in ovarian cancer have had mixed results, but on the balance provide hope for a potential synergistic role of IL-6 inhibition with standard chemotherapy." (PMID 38689325, 2024). "Despite similar cancer sizes, TLR5-responsive mice exhibited significantly higher serum IL-6 levels, and ovarian cancer progressed more rapidly than in the TLR5-dificient mice." (PMID 38541242, 2024). "Interleukin-6 (IL-6) is a multifunctional cytokine that significantly influences the development of ovarian cancer through complex pathways." (PMID 39061859, 2024). "Antibiotic treatment eliminating symbiotic bacteria erased the difference in serum IL-6 levels and dissimilarity in tumor growth, affirming the impact of the microbiome on ovarian cancer." (PMID 38541242, 2024). "Ovarian cancer cells within the OC-TME are direct producers of IL6, which they use in an autocrine manner to sustain their growth and survival." (PMID 39766086, 2024). "Four clinical trials have examined the use of monoclonal antibody IL-6 pathway inhibitors in treating ovarian cancer." (PMID 38689325, 2024). "An association between IL-6 and ovarian cancer has been described in the literature for over 30 years, beginning with the observation of IL-6 production by ovarian cancer cell lines, primary ovarian tumors and malignant ascitic fluid." (PMID 38689325, 2024). "In ovarian cancer mouse models, silencing of thrombopoietin and IL-6 reduced levels of thrombocytosis, suggesting that thrombopoietin and IL-6 are the major drivers of thrombocytosis in ovarian cancer." (PMID 39518024, 2024). "Based on these findings, IL-6 and its pathway have gained increasing interest as a potential therapeutic target in ovarian cancer." (PMID 38689325, 2024).
ovarian carcinoma (continued). "For instance, one study found that ovarian cancer cells increased the production of IL-6, which stimulated the production of VEGF, which in turn caused lymphatic vessels to form in the peritoneum, facilitating the spread of cancer cells." (PMID 38689325, 2024). "Various adipokines, including IL-6, IL-8, and fatty acids, secreted from the omental adipocytes enhance the adaptation of ovarian cancer cells by promoting proliferation and metastasis." (PMID 38540217, 2024). "For better estimation in diagnosis of ovarian cancer, correlations of Il-6 concentration with other parameters were performed." (PMID 37373969, 2023). "Relatedly, anti-inflammatory evidence of withaferin A has been shown in ovarian cancer cells by suppressing the secretion levels of various pro-inflammatory cytokines, such as tumor necrosis factor-alpha (TNFα), IL-6, IL-8, and IL-18 in ovarian cancer cells." (PMID 37110423, 2023). "In ovarian cancer, IL6 has a direct stimulus towards cancer cells via various mechanisms that contribute to the cell cycle and cancer cell growth." (PMID 37792745, 2023). "Paraneoplastic thrombocytosis in ovarian cancer is due to IL-6 originating from cancer cells and consequent thrombopoietin released from the liver." (PMID 36831623, 2023). "The secretion of IL-6, involved in the induction of proliferation in ovarian cancer, was significantly downregulated by EGCG and I3C (80% and 32.5%, respectively, p < 0.05)." (PMID 37509102, 2023). "IL-6 signaling in ovarian cancer cells can regulate tumor cell proliferation, invasion, angiogenesis, and chemoresistance." (PMID 37175439, 2023). "We have shown in a recently published paper that IL-6 in ovarian cancer ascites promotes the upregulation of TNFR2 on T cells, predominantly on Tregs, with the neutralisation of the bioactive IL-6 decreasing the proportion of TNFR2." (PMID 36765633, 2023). "A three-marker panel of GDF-15, IL-6, and IL-6 R alpha was initially identified to differentiate primary or recurrent ovarian cancer from healthy controls." (PMID 37357306, 2023). "In our study, we observed statistical significance of Il-6 in the diagnosis of ovarian cancer (p-value = 0.0412)." (PMID 37373969, 2023). "Ruxolitinib in combination tocilizumab, antibodies against IL-6, show improved survival ovarian cancer tumors in vivo." (PMID 37305676, 2023). "Numerous studies analysing molecular mechanisms of platinum resistance in ovarian cancer have reported that the over-expression of IL-6 is one of the contributing factors for chemo-resistance and poor prognosis via STAT3-mediated activation." (PMID 36765633, 2023). "Our results show that the specificity of serum TNF‐α in predicting recurrence in ovarian cancer patients and the area under the ROC curve are higher than IL‐6 and IFN‐γ." (PMID 37904699, 2023). "The aim of this study was to confirm the role of Il-6 in the diagnosis of ovarian cancer and its prognostic role in overall survival." (PMID 37373969, 2023). "According to the theory of the inflammatory background of neoplastic diseases, inflammatory markers such as C-reactive protein, procalcitonin and interleukin-6 have a potential prognostic role in diagnosis of ovarian cancer." (PMID 37373969, 2023). "In our study, we also observed and evaluated the concentration of Il-6 in advanced stages of ovarian cancer with metastases in the abdominal cavity and lungs and in metastatic tumors located in the ovaries." (PMID 37373969, 2023). "According to another report, ovarian cancer cells use the Akt/nuclear factor kappa B (NF-kB) pathway to produce IL-6, IL-8, and VEGF." (PMID 36903316, 2023). "In the case of IL-6-induced EMT signalling in ovarian cancer, receptor interacting protein serine/threonine kinase 4 (RIPK4) has been reported to be of significance." (PMID 36766756, 2023).